BCL2 (BCL2 apoptosis regulator)
Diseases named in the same sentence as BCL2 in open-access papers (continued):
Sharing a sentence is not in itself a finding about the gene and the disease.
lung carcinoma (continued). "Further studies showed that 24–48 h treatment of EVO at 20–40 μM significant inhibited cell growth and increased apoptosis with the activation of caspases-9, -3, and -8 and DR5 and the alteration of the ratio of Bax/Bcl-2 in human lung cancer A549 and H1299 cells." (PMID 31354479, 2019). "MiR‐181a targets apoptotic genes such as Bcl‐2 in acute lung injury and also in lung cancer." (PMID 30548184, 2019). "Results showed that Cal14.1a induces a high Bax/Bcl-2 ratio in H1299 (lung cancer cells)." (PMID 31861952, 2019). "The high expression of Bcl-2 anti-apoptotic protein and the low expression of Bax pro-apoptotic protein can inhibit cell apoptosis, prolong cell survival, and increase cell number, which are one of the important mechanisms of lung cancer." (PMID 31601012, 2019). "Knockdown of c‐MYC in CPA4‐overexpressing cells blocked the increase of Bcl‐2 and restored the expression of P27, indicating that c‐MYC may be the cause of CPA4 promoting lung cancer growth." (PMID 31397502, 2019). "Multidrug resistant lung cancer H69AR cells also express high levels of Bcl-2." (PMID 29899843, 2018). "Bcl-2 expression alone can confer paclitaxel resistance in H460 lung cancer cells." (PMID 29899843, 2018). "Although the decrease of Mcl-1 and Bcl-2 was notified after treatment with avicequinone B at 1–4 μM, the significantly reduction of caveolin-1 and induction of anoikis were only observed in human lung cancer cells incubated with avicequinone B at 4 μM." (PMID 29631569, 2018). "In conclusion, these results of our study suggest that Biochanin A can inhibit the proliferation of lung cancer cells by inducing lung cancer cells cell cycle arrest and apoptosis mainly by regulating S phase-related protein expression and activating the Bcl-2 and Caspase-3 pathways." (PMID 30402472, 2018). "The results of the present study showed that polydatin induces apoptosis effectively with an increase in Bax expression and a decrease in Bcl-2 expression in lung cancer cells, providing a theoretical basis for the prevention and treatment of lung cancer by polydatin." (PMID 30584449, 2018). "However, the expression levels of the antiapoptotic protein, bcl-2, was decreased in the lung cancer cells by IL-32γ." (PMID 29467412, 2018). "In this study, LSS-11 significantly increased the levels of DR5 and cleaved PARP1, proteins mainly involved in death-receptor-mediated apoptosis, but did not affect mitochondria-associated Bax or Bcl2 proteins in paclitaxel-resistant lung cancer cells." (PMID 29072615, 2017). "In addition, this agent increased cleavage of PARP, Bax and cacspase-3 activity whereas it decreased Bcl-2 in lung cancer cells." (PMID 28099148, 2017). "Incremental changes in pro-apoptotic Bax and decreased changes anti-apoptotic Bcl-2 protein levels were also observed, suggesting that complex 3 may modulate apoptosis in A549 lung cancer cells." (PMID 28427237, 2017). "In summary, the findings from this study highlight the potent effects of peptides extracted from fruiting bodies of L. squarrosulus mushroom, in mediating apoptosis in lung cancer cells through the decrease of anti-apoptotic Bcl-2 and c-FLIP proteins and increase of pro-apoptotic protein Bax." (PMID 28532227, 2017). "Here we studied the cytotoxic properties of s-cal14.1a in four lung cancer cell lines, we quantified the expression of genes involved in execution and regulation of apoptosis namely Bcl-2, BAX and the pro-survival proteins NFκB-1 and COX-2, we also analyzed caspase activity." (PMID 26861394, 2016).
lung carcinoma (continued). "Moreover, Bcl-2 up-regulation is particularly obvious during the progression from pre-invasive lesions to invasive carcinoma in lung cancer samples." (PMID 26621844, 2016). "MiR-503 regulates the resistance to cisplatin in lung cancer by targeting Bcl-2." (PMID 27083050, 2016). "Our study showed that exogenous miR-206 could down-regulate the expression of c-Met and Bcl2 protein and mRNA in lung cancer cells." (PMID 26325180, 2015). "Moreover, up-regulation of miR-206 suppresses lung cancer cell migration, invasion and colony formation, and promotes lung cancer cell apoptosis, through targeting c-Met and Bcl2." (PMID 26325180, 2015). "In addition, inhibition of Bcl2 expression promoted apoptosis in lung cancer cell (both A549 and SK-MES-1 cells)." (PMID 26325180, 2015). "In present study, we provide evidences firstly indicate that TIPE2 suppresses the growth and promotes apoptosis of lung cancer through regulating the Bcl-2/Bax balance and then leads to the activation of caspase-3 and caspase-9 possibly via affecting P38 and Akt pathway." (PMID 25946186, 2015). "Bcl2 partially co-localizes with APE1 in the mitochondria of human lung cancer cells." (PMID 26268226, 2015). "In both gastric and lung cancer cell lines, miR-497 modulates apoptosis by targeting Bcl2." (PMID 26299920, 2015). "Collectively, our experimental data may provide a strategy for targeting the miR-206/c-Met or miR-206/Bcl2 interaction in a novel therapeutic application to treat lung cancer patients." (PMID 26325180, 2015). "We next examined the potential tumorigenicity of MET and BCL2 in lung cancer." (PMID 26325180, 2015). "Furthermore, the c-Met and Bcl2 mRNA and protein were over-expressed in lung cancer tissues compared with normal tissues." (PMID 26325180, 2015). "NNK can stimulate the functional cooperation of Bcl2 and c-Myc via phosphorylation, which may promote lung cancer development." (PMID 24967145, 2014). "In NSCLC tissues, many onco-miRs/tumor suppressor-target or tumor suppressor-miRs/onco-target pathways have been demonstrated to participate in the tumorigenesis of lung cancer, including miR7/BCL2 axis, miR-99b/FGFR3 axis, miR-101/EZH2 axis, miR-192/RB1 axis and miR-196/HOXA5 axis." (PMID 25012722, 2014). "Additionally, NNK simultaneously induces both Bcl2 phosphorylation and c-Myc phosphorylation, which promote functional cooperation of these two oncogenic proteins in lung cancer development." (PMID 24967145, 2014). "Furthermore, our studies showed that lung cancer cells with deficient FA pathway were more sensitive to treatment with a CHK1-kinase pathway inhibitor and a BCL-2/XL inhibitor." (PMID 25566506, 2014). "In summary, our results demonstrate that the klotho, an anti-aging gene, is associated with the resistance of lung cancer cells to cisplatin and may alleviate the resistance mainly through modulating the PI3K/Akt signal pathway and the expression of bax/bcl-2." (PMID 23437382, 2013). "It was reported that miR-200bc/429 cluster could play a role in the development of MDR in both gastric and lung cancer cell lines via targeting BCL2 and XIAP." (PMID 23372675, 2013). "In most lung cancers, one main mechanism of cancer cell resistant is the so-called non-pump drug resistance that is primarily due to the activation of anti-apoptotic cellular defense of lung cancer cells, and Bcl-2 is thought to be a key player in this defense." (PMID 23977251, 2013). "Studies of Bcl2 were also carried out in the solid tumors, including lung cancer." (PMID 23977251, 2013). "Additionally, NO inhibited Bcl-2 ubiquitin-dependent degradation to restore Bcl-2 protein level in human lung carcinoma H-460 cells." (PMID 22629368, 2012).
lung carcinoma (continued). "Our validated model may be useful for prognostic stratification of lung cancer patients as well as incorporation of Bcl-2 into clinical decisions." (PMID 20459695, 2010). "Alternatively, other antiapoptotic molecules such as bcl-2 proteins may be more important players in lung cancers." (PMID 15266313, 2004). "In contrast, transregulatory mechanisms appear to be responsible for the high levels of Bcl-2 protein production that occur in many different solid tumours such as prostate cancer, breast cancer and lung cancer." (PMID 12838300, 2003). "The role of the anti-apoptotic protein Bcl-2 in lung cancer remains controversial." (PMID 12838300, 2003). "Moreover, L-pimaric acid could induce the death of drug-resistant lung cancer cells by downregulating Bcl-2, upregulating Bax, activating the p38 MAPK/JNK signaling pathways, and inhibiting the ERK pathway." (PMID 41011239, 2025). "This study aimed to investigate the antiproliferative, apoptotic, and antioxidant effects of AP on human lung adenocarcinoma cells (A549) and to investigate the effects on Bax, Bcl-2, NF-κB, and caspase-3 signaling pathways that may play a role in the pathogenesis of lung cancer." (PMID 39945813, 2025). "Furthermore, H460 lung cancer cells which have high levels of endogenous Bcl-2 expression, when treated with BFC1108, exhibited a decrease in mitochondrial membrane potential upon staining with JC-1 dye, indicating the collapse of the mitochondrial outer membrane." (PMID 38329389, 2024). "In vitro, TLR8 agonist stimulation of lung cancer cells resulted in the activation of NF‐κB, increased expression of proinflammatory factors (IL‐6, IL‐8, GM‐CSF, IL‐1α, and IL‐12), and increased expression of antiapoptotic proteins Bcl‐2, VEGFR2, and chemokine receptors." (PMID 39003635, 2024). "In addition, Eug inhibited the expression of Bcl-2 protein in lung cancer cells." (PMID 37896013, 2023). "Similarly, genistein may enhance the production of Bax and down‐regulate Bcl‐2, as well as inhibit lung cancer cell proliferation and induce their apoptosis." (PMID 37697969, 2023). "In addition, the overexpression of BCL-2 is an early event in the development of lung cancer." (PMID 36313628, 2022). "Similarly, METTL3 has been shown to mediate apoptosis by regulating Bcl-2 in lung cancer." (PMID 35141221, 2022). "However, EGFR inhibition may result in an activation of the compensatory pro-survival signaling in tumors, including antiapoptotic protein BCL2 upregulation in lung cancer cells." (PMID 36361596, 2022). "We next analyzed the protein expression of oncogenes known to be transcriptionally upregulated in tuft cell-like lung cancer subsets, i.e., BCL2, MYC, and KIT, because their expression might further delineate tuft cell-like variants and open new therapeutic perspectives." (PMID 36402755, 2022). "For example, Inonotus obliquus polysaccharides (IOP) could activate AMPK in a concentration‐depend manner and induce apoptosis of LLC1, A549‐LKB1 lung cancer cells while down‐regulating Bcl‐2, up‐regulating Bax protein expression, and enhancing the cleavage of Caspase3 and PARP." (PMID 33841805, 2021).
lung carcinoma (continued). "The treatment of A549 cells with ABN-B increased the levels of cleaved PARP and caspase-7, but decreased the expression level of anti-apoptotic Bcl-2 protein in a concentration-dependent manner, indicating that this compound may have the ability to induce apoptosis in human lung cancer cells." (PMID 33327489, 2020). "To investigate whether miR-216b can increase BCL-2 expression and promote resistance of lung cancer cells to anti-cancer drugs by downregulating Smad3 expression, we established NCI-H460 human NSCLC cell clones by stably expressing miR-216b using lentiviral vector plenty-III-GFP pri-mir-216b." (PMID 32668597, 2020). "The miR-630 expression levels were also evaluated in a panel of lung cancer cells to select cells that showed high and a low expression of miR-630 for miR-630 manipulation and to verify whether miR-630 might modulate cisplatin sensitivity by targeting Bcl-2." (PMID 29568392, 2018). "Moreover, Chatterjee also demonstrated that overexpression of miR-16 could sensitize paclitaxel resistant lung cancer cells to paclitaxel by inducing apoptosis via inhibiting anti-apoptotic protein Bcl-2." (PMID 28915618, 2017). "Silencing of Rrm1 and Rrm2 markedly enhanced the cytotoxicity of the topoisomerase I inhibitor camptothecin that might be exploited in chemotherapeutic strategies and RRM2 was shown to regulate Bcl-2 in lung cancers and considered to be a worthy target in cancer therapy." (PMID 27602772, 2016). "Coincidently, RRM2 could also increase Bcl-2 protein stability in Head and Neck and Lung Cancers." (PMID 27801665, 2016). "Furthermore, venetoclax, a BCL2-specific inhibitor, is unable to reproduce the effects of navitoclax (BCL2/BCLXLi), suggesting that in agreement with the reported findings in lung cancer, it is BCLXL that protects against apoptosis upon targeted inhibition of a mutant RAS pathway in CRC organoids." (PMID 27845624, 2016). "Moreover, Bcl-2 de-targeted by miR-184 reduction may be responsible for E6-mediated cisplatin resistance in cervical and lung cancer cells." (PMID 27083050, 2016). "Taken together, TIPE2 promoted lung cancer cell apoptosis through affecting apoptosis-related molecules caspase-3, caspase-9, Bcl-2 and Bax, possibly via regulating P38 and Akt pathways, indicating that TIPE2 might be a novel marker for lung cancer diagnosis and therapy." (PMID 25946186, 2015). "Therefore, novel therapeutic strategies for lung cancer in which Bcl2 is expressed may be used to abrogate the antiapoptotic activity of Bcl2 by inhibiting multiple upstream nicotine-activated pathways." (PMID 24967145, 2014).
lung carcinoma (continued). "Nicotine-/NNK-induced phosphorylation of Bcl2 and Mcl-1 enhances their antiapoptotic functions, while phosphorylation of Bax and Bad inactivates their proapoptotic functions, which contributes to increased survival and chemoresistance of human lung cancer cells." (PMID 24967145, 2014). "Moreover, although high NO levels down-regulate the antiapoptotic protein Bcl-2 and induce cytotoxicity in e.g., B16M-F10 cells, low NO levels induce S-nitrosylation of Bcl-2, which inhibits its ubiquitination and subsequent proteosomal degradation in, for example, lung cancer cells." (PMID 24281071, 2010). "In fact, we found that in lung cancer over expression of BCL2 could be explained by the under expression of MIR15A, MIR16-1, and MIR16-2, while in kidney tumours over expression of DFFB, HTATIP and RELA could be related to the under expression of MIR124A-1, MIR124A-2, and MIR124A-3." (PMID 19402918, 2009). "The results need to be confirmed by an adequately designed prospective study and the exact value at which Bcl-2 should be considered ‘overexpressed’ determined by an appropriate multivariate analysis taking into account the classical well-defined prognostic factors for lung cancer." (PMID 12838300, 2003). "O. gratissimum extract induced apoptosis in A549 lung cancer cells by activating caspases and modulating BAX and BCL-2 levels." (PMID 40218923, 2025). "In lung cancer, CEBPA enhances the transcriptional expression of LOXL2/LOXL3 and stabilizes BCL-2, thereby promoting the initiation and progression of lung cancer." (PMID 41250755, 2025). "It is implicated in the sensitivity of colorectal cancer cell lines to cetuximab, and in lung cancer cells, it potentially leads to cisplatin resistance via ERK-mediated Bcl-2 transcriptional activation." (PMID 40821990, 2025). "LOXL2 was shown by Fan and colleagues to promote lung cancer metastasis and progression via CEBPA‐mediated upregulation, which inhibits BCL‐2 degradation." (PMID 41395115, 2025). "PTX is known for inducing lung cancer apoptosis, hence we tested the effect of these EVs in modulating PTX-induced A549 apoptosis by measuring caspase 3/7 activity and Bax:Bcl-2 level." (PMID 41271627, 2025). "The synergistic effects of triptolide when used alongside other medications, such as EGFR inhibitors in lung cancer, TRAIL receptor agonists in renal cell carcinoma, and Bcl-2 inhibitors in leukemia, further highlight its therapeutic promise." (PMID 40490812, 2025). "TriC has also shown additive or synergistic effects with other therapies (e.g., increasing sensitivity to gemcitabine in pancreatic and lung cancer cells and synergizing with ABT‐199, the FDA‐approved BCL‐2 inhibitor, in AML cells)." (PMID 39853696, 2025). "Combined with the Bcl-2 inhibitor venetoclax, BKA-073 demonstrates synergistic effects, indicating the potential of Bak activators as a novel class of lung cancer therapies." (PMID 40841912, 2025). "The cytotoxicity assay and the ELISA to assess the levels of BAX, BCL-2, TGF-β and FR-ɑ after the MTX, ABL and the optimized MTX-ABL solid dispersion groups were tested against lung cancer cells, A549 cells, for 24 h." (PMID 39821171, 2025). "In non‐small cell lung cancer, the dual application of ABT‐263, which also inhibits Bcl‐2, Bcl‐xl, and Bcl‐w, with gemcitabine has shown improved therapeutic outcomes by effectively reducing tumor growth and increasing survival rates in preclinical models." (PMID 40405831, 2025). "By upregulating pro-inflammatory cytokines, anti-apoptotic protein Bcl-2, and angiogenesis-related VEGFR2, TLR7 activation in lung cancer increases tumor cell survival and resistance to apoptosis." (PMID 38850110, 2024). "Multiple under-expressed proteins were also predictable to a great extent, the top-performing ones being CASP8, MET, BCL2, and SETD2 in BRCA; AR and TFRC in gastric cancer; and VHL in lung cancer with AUCs ranging 0.814–0.866." (PMID 38491101, 2024).